ABCB5 (ATP binding cassette subfamily B member 5)
Diseases named in the same sentence as ABCB5 in open-access papers (continued):
Sharing a sentence is not in itself a finding about the gene and the disease.
breast carcinoma (16 papers, 2010 to 2025). "In breast cancer patients, the ABCB5 SNP rs3210441 was associated with response to neoadjuvant cytotoxic therapy and ABCB5 expression in TCGA was associated with anthracycline resistance." (PMID 39267923, 2024). "In patients with primary tumors of breast cancer, hydralazine (a DNA demethylation agent) and magnesium valproate up- and downregulate 1091 and 89 genes, respectively, by at least 3-fold; ABCB5 was only downregulated." (PMID 41020871, 2025). "In breast cancer, ABCB5 is also overexpressed at the transcriptional level and can enhance metastasis and epithelial–mesenchymal transition (EMT) through the expression of ZEB1." (PMID 41020871, 2025). "In breast cancer, overexpression of ABCB5 significantly promotes the migration, invasion, and EMT cascade." (PMID 40746888, 2025). "Patients with resistant acute myeloid leukemia, breast cancer, and Merkel cell carcinoma had increased expression of ABCB5 mRNA after standard treatment with chemotherapeutic agents." (PMID 39267923, 2024). "Studies have reported that ABCB5, ABCB8, ABCB10, ABCC2–5, and ABCC10 are overexpressed in breast cancer cells or are associated with breast cancer progression." (PMID 30202239, 2018). "In addition, we found that exogenous expression of ΔNp73 led to an increase in the expression of ABCB1 and ABCB5 in the breast cancer-derived cell lines tested, while knocking down of ΔNp73 resulted in a reduction in ABCB1 and ABCB5 expression." (PMID 28677036, 2017). "Furthermore, upon EMT, TGF-β treatment could upregulate the ABCB5 expression in breast cancer cells." (PMID 40746888, 2025). "Using Western blotting, without specifying the antibody used, and RT-qPCR, it was shown that non-invasive breast cancer cell lines (MDA-MB-468 and MCF7) had decreased expression of ABCB5 compared to an invasive cell line (BT549)." (PMID 39267923, 2024). "For, breast cancer dataset, two genes HSPA1A and ABCB5 detected by the proposed gsslasso method were also detected by other method." (PMID 30813883, 2019). "ABCB1, ABCB5, ABCB8, ABCC1, ABCC2, ABCC3, and ABCG2 were considered to confer resistance to doxorubicin on the breast cancer cells." (PMID 30202239, 2018). "Variant rs3210441 in ABCB5 associated with response to NACT in our study, but no eQTL was found and additional supportive data about the role of this SNP or protein in breast cancer is lacking." (PMID 33334016, 2020). "In doxorubicin-resistant breast cancer cells that have high levels of ABCB5, ERK-3 serine/threonine kinase is specifically upregulated, suggesting that ABCB5 and ERK3 could be potential targets against drug-resistant breast cancer cells." (PMID 29929490, 2018). "Our work provides valuable insight into the drug induced cell fusion event and outcome, and suggests YB-1, GST, ABCB5 and ERK3 could be potential targets for the anti-cancer drug development against drug resistant breast cancer cells." (PMID 20649952, 2010). "We found that bromocriptine was cytotoxic towards drug-sensitive CCRF-CEM, multidrug-resistant CEM/ADR5000 leukemic cells as well as wild-type or multidrug-resistant ABCB5-transfected HEK293 cell lines, but not sensitive or BCRP-transfected multidrug-resistant MDA-MB-231 breast cancer cells." (PMID 30349477, 2018).
colon cancer (14 papers, 2015 to 2025). "It was also suggested that the expression level of ABCG2 and ABCB5 decreased following c-myc silencing and sensitized colon cancer stem cells to chemotherapy." (PMID 34536148, 2021). "A number of studies have shown the role of ABCB5 in the implementation of resistance and functioning of cancer stem cells of such types of such solid tumors as that of the oral cavity and colon cancer." (PMID 33925224, 2021). "In this study, we showed that c-MYC confers resistance to 5-FU by regulating ABCB5 expression in human colon cancer cells." (PMID 25689483, 2015). "ABCB5 knockdown decreased the survival rate following 5-FU treatment as expected, and the ABCB5 expression level was increased in 5-FU-resistant human colon cancer cells." (PMID 25689483, 2015). "Another possibility is that 50-FU treatment increases ABCB5 expression in some population of colon cancer cells, and the colon cancer cells with the increased ABCB5 expression can survive." (PMID 25689483, 2015). "One possibility is that some population of colon cancer cells which originally have high ABCB5 expression survive following 5-FU treatment." (PMID 25689483, 2015). "Taken together, these results suggest that c-MYC confers resistance to 5-FU through regulating ABCB5 expression in human colon cancer cells." (PMID 25689483, 2015). "Furthermore, the combined drug treatment caused 22-fold induced expression of miRNA522-5p, and this miRNA reverses drug resistance of doxorubicin-induced HT29 colon cancer cell by targeting ABCB5." (PMID 37208732, 2023). "Remarkably, miR‐522 could also sensitize colon cancer cells to doxorubicin treatment by targeting ABCB5, indicating its proliferation‐inhibiting property under specific circumstances." (PMID 33369228, 2021). "Interestingly, it has been reported that decreasing expression of ABCG2 and ABCB5 may induce the depletion of c-Myc and enhance the chemosensitivity of colon cancer stem cells (CSCs)." (PMID 34381520, 2021). "For example, in colon cancer, cell surface markers such as CD133, CD44, ALDH and ATP-binding cassette sub-family B member 5 (ABCB5) were reported to be a identification of CSCs." (PMID 30962766, 2019). "ABCB5, Lgr5, CD133, and CK20 gene expression in bone marrow collected from patients with colon cancer was further quantified and tested for their influence on overall survival in the patients." (PMID 34221246, 2017). "No genomic insertions, deletion, or rearrangements were detected in ABCG2+/ABCB5+ LESCs; however, genetic abnormalities were detected in SW620 colon cancer cells." (PMID 29230251, 2017). "In this study, we identified ABCB5 as a novel c-MYC target gene and examined the role of the c-MYC-ABCB5 axis in 5-FU resistance in human colon cancer cells." (PMID 25689483, 2015). "To identify the ABC transporter genes regulated by c-MYC in human colon cancer cells, we investigated the effect of c-MYC knockdown on MDR1, MRP1, ABCB5, ABCC4 and ABCC5 expression levels, which are closely involved in the resistance to chemotherapeutic agents including 5-FU 17–23." (PMID 25689483, 2015).
colorectal cancer (10 papers, 2012 to 2025). A primary or metastatic malignant neoplasm that affects the colon or rectum. "Similarly, ABCB5 mRNA in the bone marrow of colorectal cancer patients was negatively associated with tumor progression and overall survival." (PMID 39267923, 2024). "In a xenograft mouse model or in vitro culture of colorectal cancer cells, ABCB5 was shown to promote invasion and epithelial-to-mesenchymal transition (EMT)." (PMID 39267923, 2024). "Colorectal cancer patients treated with 5-FU had increased ABCB5 expression on immunohistochemistry compared to the same tissue before treatment." (PMID 39267923, 2024). "Its involvement in tumor growth is further supported by studies utilizing shRNA to knock down ABCB5 expression in colorectal cancer cell lines, which resulted in reduced tumor formation in human-to-mouse xenograft models." (PMID 39679367, 2024). "ABCB5 mRNA was upregulated in the peripheral blood of colorectal cancer patients and its expression correlated with cancer progression." (PMID 39267923, 2024). "As a drug efflux transporter, it has been shown that ABCB5 mediated anticancer drug resistance and conferred clinically relevant chemoresistance to CSCs in human colorectal cancer." (PMID 32357409, 2020). "We previously showed that the ATP-binding cassette (ABC) transporter, ABCB5, is a chemoresistance mediator expressed on specific cell subsets in colorectal cancer (CRC) and other malignancies." (PMID 34221246, 2017). "This last point was recently addressed in colorectal cancer in which ABCB5 was shown to identify a therapy-refractory tumor cell population." (PMID 22675422, 2012). "Similarly, shRNA targeting ABCB5 inhibited cancer growth and sensitized cells to 5-FU in a colorectal cancer xenograft." (PMID 39267923, 2024). "Overexpression of miR-522 in HT29/DOX cells brought about decreased levels of ABCB5 protein levels, suggesting that miR-522 mimics could be a promising treatment approach for overcoming chemoresistance in colorectal cancer." (PMID 39679367, 2024). "ABCB5 confers 5-fluorouracil resistance and promotes cell invasiveness in colorectal cancer." (PMID 33334016, 2020). "Importantly, we observed that ABCB5 expression level in primary colorectal cancer tissues did not correlate with the recurrence rate following 5-FU-based adjuvant chemotherapy." (PMID 25689483, 2015). "By detecting RNA level of LNX1 of the sorted SP and non-SP from the colorectal carcinoma cell line HT29, it was found that LNX1 was highly expressed in SP cells with higher levels of LGR5, ABCB5, ALDH1A1 and CD133 rather than non-SP group." (PMID 29190716, 2017).
metastatic melanoma (7 papers, 2012 to 2024). A melanoma that has spread from its primary site to another anatomic site. "In vitro, we showed that ABCB5-expressing cells selectively survive when exposed to dacarbazine, the reference treatment of metastatic melanoma, but also to vemurafenib, a new inhibitor of the mutated kinase V600E BRAF and other various chemotherapeutic drugs." (PMID 22675422, 2012). "Consistently, nuclear expression of PKC-θ, along with the expression of cytoplasmic CSV and ABCB5, were increased in primary metastatic melanomas from patients with progressive disease." (PMID 35326747, 2022). "Fifty-nine blood samples from 39 metastatic melanoma patients were subjected to CTC enrichment using immunomagnetic beads conjugated to anti-MCSP or anti-ABCB5 antibodies." (PMID 30769764, 2019). "The results demonstrated that CTCs from metastatic melanoma patients were highly heterogeneous and commonly expressed stem-like markers such as PAX3 and ABCB5." (PMID 28978038, 2017). "A study using immunomagnetic enrichment techniques to capture CTCs by utilization of MCAM, MCSP, ABCB5, and CD271 to compare populations of CTCs in circulation between individuals with primary and metastatic melanomas, found that CTC populations were significantly higher in metastatic melanoma." (PMID 39156972, 2024).
cutaneous melanoma (6 papers, 2012 to 2026). A primary melanoma arising from atypical melanocytes in the skin. "ABCB5 is a marker of cancer stem cells and its expression was found increased in different types of neoplasias, including colon cancer, cutaneous melanoma, hepatocellular carcinoma and Merkel cell carcinoma." (PMID 35008260, 2021). "For example, in cutaneous melanoma ABCB5 was shown to promote neoplastic invasion and distant metastases through the NF-kB pathway, in a process likely mediated through MMP9, which is involved in cancer invasion and metastasis." (PMID 35008260, 2021). "ABCB5 is a cancer stem cell marker over-expressed in cutaneous melanoma CTCs." (PMID 34885099, 2021). "In addition, ABCB5 chemoresistance mediator, CD166 activated leukocyte cell adhesion molecule, and Nestin intermediate filament protein expressed in the cytoplasm of intraepithelial stem cells, have also been reported in various stages of cutaneous melanoma." (PMID 22922842, 2012). "We analyzed data from the skin cutaneous melanoma cohort and could identify significant negative correlation between the NRF2 target malic enzyme 1 (ME1) and KIT as well as ABCB5." (PMID 34951143, 2022).
glioblastoma (6 papers, 2017 to 2025). The most malignant astrocytic tumor (WHO grade IV). "Previous investigations have shown that ABCB5 level was statistically elevated in several cancers including sinonasal mucosal melanoma and glioblastoma." (PMID 40746888, 2025). "ABCB5 modulates G2/M checkpoint regulators to promote the chemoresistance of glioblastoma." (PMID 40746888, 2025). "Similarly, blockade of ABCB5 with anti-ABCB5 mAb or downregulation with shRNA resulted in decreased proliferation of glioblastoma multiforme and sensitized cells to temozolomide in both cell culture and xenograft models." (PMID 39267923, 2024). "Likewise, ABCB5 increases resistance in CD133+ glioblastoma multiforme CSCs, and ABCB5 inhibition makes CSCs sensitive to temozolomide." (PMID 36042526, 2022).
hepatocellular carcinoma (6 papers, 2011 to 2024). A malignant tumor that arises from hepatocytes. "Expression of ATP‐binding cassette B5 (ABCB5) has been demonstrated to confer chemoresistance, enhance cancer stem cell properties and associate with poor prognosis in hepatocellular carcinoma (HCC)." (PMID 32783366, 2020). "In hepatocellular carcinoma, MDR is mediated by ABCB1, ABCB5, ABCC1, ABCC2, and ABCG2." (PMID 36557005, 2022).
diabetic foot ulcers (4 papers, 2022 to 2025). "Translational development of ABCB5+ dermal mesenchymal stem cells for therapeutic induction of angiogenesis in non-healing diabetic foot ulcers." (PMID 39927093, 2025).
lung carcinoma (4 papers, 2020 to 2022). "Interestingly, lung cancer cells with mutations of resistant genes, such as ABCB5, IGFBP5, MAP4, showed high proliferation treatment by drug AZD7762." (PMID 36180906, 2022).
oral cancer (4 papers, 2013 to 2025). "As shown, the expression of ABCB5 in oral cancer cell lines was significantly upregulated as compared with the HOK, both in gene levels using qRT-PCR and in protein levels identified via western blot." (PMID 40746888, 2025). "Since our data suggested that LINC00963 contributed to the aggressiveness and chemoresistance of oral cancer via the downregulation of ABCB5, it is plausible to speculate that Akt may play a role in the LINC00963-regulated ABCB5 expression." (PMID 32357409, 2020). "Interestingly, ABCB5 marks a putative cancer stem cell compartment in oral cancer, and cancer stem cells of the laryngeal cancer cell line Hep-2 show an increase in ABCG2 expression." (PMID 23626764, 2013). "To study the function of ABCB5 in OSCC, we first determined the levels of ABCB5 in the CAL27 and HSC-3 oral cancer cell lines, and HOK." (PMID 40746888, 2025). "A recent study further revealed that in oral squamous cell carcinoma (OSCC) and oral cancer stem cells (CSCs), elevated levels of Long Intergenic Non-Protein Coding RNA 963 (LINC00963) drive malignant progression and drug resistance through the regulation of ABCB5." (PMID 40445912, 2025).
oral squamous cell carcinoma (4 papers, 2016 to 2025). "The clinical significance of ABCB5 has been extensively documented, showing strong correlations between its expression and poorer patient outcomes, such as increased tumor progression and reduced overall survival in colorectal and oral squamous cell carcinomas." (PMID 40445912, 2025).
prostate carcinoma (4 papers, 2017 to 2024). A carcinoma that arises from epithelial cells of the prostate gland. "ABCB5 expression was the highest in carcinomas of the prostate, pancreas, breast, lung, kidney, liver, and stomach, while the others showed a high interindividual variation of ABCB5 expression." (PMID 39267923, 2024). "ONC201 significantly downregulated CSC-related genes ABCB5, ALDH1A1, ALDH7A1, WNT16, CD133 and NANOG in DU145 prostate cancer cells." (PMID 28767654, 2017).
atherosclerosis (3 papers, 2022 to 2024). A disease characterized by the build-up of fatty material and calcium deposition in the arterial wall resulting in partial or complete occlusion of the arterial lumen. "In atherosclerosis, ABCB5 mRNA expression in microarray was increased in the plaques of high-risk patients compared to low-risk patients." (PMID 39267923, 2024). "However, all these studies do not present direct evidence, but only correlations, and more research is needed to understand the role of ABCB5 in atherosclerosis, ischemic stroke outcome, cardiomyopathy, childhood obesity, and attention deficit hyperactivity disorder." (PMID 39267923, 2024). "ABCB5, a gene previously not studied in the context of atherosclerosis, emerged as one of the top upregulated in plaques from both high-risk CAR and ABCD2 patients." (PMID 35494231, 2022). "ABCB5, previously not described in the context of atherosclerosis, was one of the top genes identified by both high CAR and ABCD2 risk scores, localized to macrophages, IPH, and neovessels in plaques from symptomatic patients." (PMID 35494231, 2022).
epidermolysis bullosa (3 papers, 2021 to 2022). Epidermolysis bullosa (EB) is a group of genetic skin diseases that cause the skin to blister very easily. "A recent trial evaluating intravenously injected ABCB5+ allogeneic skin-derived hMSCs in patients with epidermolysis bullosa reported two patients with severe, yet transient and manageable, hypersensitivity reactions." (PMID 36059533, 2022).
liver cancer (3 papers, 2011 to 2025). An epithelial or non-epithelial malignant neoplasm that arises from the liver. "Liver cancer cells overexpressing ABCB5 had decreased uptake of doxorubicin and siRNA against ABCB5 sensitized cells to doxorubicin." (PMID 39267923, 2024). "In addition, we have shown recently that ABCB5 regulated hepatic cancer stem cell markers CD133 and EpCAM." (PMID 22194816, 2011). "Liver cancer cell lines, isolated based on their GEP and/or ATP-dependent binding cassette (ABC) drug transporter ABCB5 expression, were evaluated for hepatic CSC properties in terms of colony formation, chemoresistance and tumorigenicity." (PMID 22194816, 2011).
ocular surface squamous neoplasia (3 papers, 2016 to 2024). "In addition, ABCB5 recently was found upregulated in ocular surface squamous neoplasia, although limited sample size and varying ABCB5 expression patterns did not allow proper evaluation of the relationship between ABCB5 expression and tumor formation." (PMID 33741066, 2021). "Because of the ABCB5 expression pattern in tumors of cancer patients and because multidrug resistance is rarely seen in ocular surface squamous neoplasia where ABCB5 is overexpressed, the hypothesis that ABCB5 may be involved in tumor progression is strengthened." (PMID 39267923, 2024).
rectal cancer (3 papers, 2015 to 2018). A primary or metastatic malignant neoplasm that affects the rectum. "Moreover, we found overexpression of ABCB5 in a subset of 5-FU-refractory cells in primary tumor specimens resected from patients with rectal cancer after neoadjuvant radio chemotherapy." (PMID 34221246, 2017).
cyst (2 papers, 2022). A sac-like closed membranous structure that may be empty or contain fluid or amorphous material. "Therefore, ABCB5+ MSCs might represent a potential candidate therapeutic for reducing cyst growth and improving kidney function in PKD." (PMID 36613507, 2022).
cystic kidney disease (2 papers, 2022 to 2023). A congenital or acquired kidney disorder characterized by the presence of renal cysts. "Because ABCB5+ MSCs showed similar therapeutic benefit to ASCs in cystic kidney disease in our previous study, we compared the effects of clinical-grade human ABCB5+ MSCs to human ASCs in our current models." (PMID 38274791, 2023).